CD36 (CD36 molecule (CD36 blood group))
Diseases named in the same sentence as CD36 in open-access papers (continued):
Sharing a sentence is not in itself a finding about the gene and the disease.
endometriosis (9 papers, 2011 to 2025). The growth of functional endometrial tissue in anatomic sites outside the uterine body. "The inhibition of phagocytosis ability of macrophages is also noted in patients with endometriosis, due to lower expression of CD36 caused by prostaglandin E2, possibly playing a role in the development of the disease." (PMID 32751735, 2020). "An increased expression of CD200 correlates with reduced phagocytic activity and decreased CD36 expression in endometriosis (human)." (PMID 40508002, 2025). "These fragments are recognized by scavenger receptors, including CD36, whose expression is decreased in women with endometriosis." (PMID 39894821, 2025). "Increased prostaglandin E2 inhibits the expression of annexin A2 and CD36 in peritoneal macrophages, weakening phagocytosis in patients with endometriosis and, thereby, contributing to its pathogenesis." (PMID 39894821, 2025). "Particularly noteworthy is the study of reduced expression for the CD36 thrombospondin receptor in the peritoneal macrophages of women with endometriosis, reducing their phagocytosis ability." (PMID 39857742, 2025). "Activation with rosiglitazone resulted in an increase in CD36 expression in macrophages in both control and endometriosis exosome-treated cells." (PMID 39062452, 2024). "CD36 downregulation decreases the phagocytic ability of macrophages in the peritoneum of women with endometriosis." (PMID 36802172, 2023). "The expression of the macrophage receptor CD36 was downregulated after exosomes of the uterine aspirate fluid were taken from the endometriosis intervention." (PMID 36551866, 2022). "We speculate that exosomes from the uterine cavity in endometriosis may affect the phagocytosis of macrophages to ectopic lesions by downregulating the expression of CD36 in peritoneal macrophages." (PMID 36551866, 2022). "On the other hand, CD36, a scavenger receptor involved in multiple physiological processes, including the clearance of oxidized low-density lipoprotein and apoptotic neutrophils, has significant lower expression in pMφ of women with endometriosis." (PMID 34639133, 2021). "Furthermore, CD36 blockade impairs the phagocytic ability of normal Mφ; and its overexpression restores the phagocytic capacity of Mφ from women with endometriosis." (PMID 34639133, 2021). "Hence, it has been described that there is a lower expression of CD36 in pMφ of women with endometriosis, producing a lower efficiency to eliminate apoptotic cells compared to that of Mφ from healthy women." (PMID 34639133, 2021). "With PPARG expression being induced by endometriosis sEVs, we aimed to assess the effect of pharmacological activation of PPARG on CD36 and the macrophage phenotype." (PMID 39062452, 2024). "The expression of CD36 was decreased after interfering with exosomes of the uterine aspirate fluid in patients with endometriosis, while the expression of SIRP-α was not affected." (PMID 36551866, 2022). "In the case of PPARG, macrophages treated with sEVs from endometriosis also showed higher expression levels than those treated with sEVs from controls, although in this case, it was not accompanied by any change in the expression of CD36, one of the genes commonly induced by PPARG activation." (PMID 39062452, 2024). "TGF-β could also modulate the expression of CD36, since inhibition of TGF-β in THP-1 cell-derived macrophages treated with a eutopic endometrial homogenate, improved the expression of CD36, therefore TGF-β could be a potential therapeutic target for the treatment of endometriosis." (PMID 34639133, 2021).
renal fibrosis (9 papers, 2020 to 2025). A final common manifestation of a wide variety of chronic kidney diseases characterized by glomerulosclerosis and tubulointerstitial fibrosis. "The severity of renal fibrosis in macrophage CD36-deficient mice was significantly lower than that in wild mice." (PMID 35517820, 2022). "Pharmacological or genetic CD36 inhibition prevents renal fibrosis in experimental models, positioning CD36 as a therapeutic target." (PMID 40725208, 2025). "In high-fat and high-glucose conditions, excess fatty acids transported by CD36 promote renal fibrosis in HK-2 cells." (PMID 39857243, 2024). "In additional studies, CD36 was also shown to play a role in skin scarring, pulmonary fibrosis, and renal fibrosis." (PMID 37593175, 2023). "Targeting CD36 can prevent renal fibrosis and reduce CKD progression." (PMID 39857243, 2024). "An high glucose stimulated CD36-dependent Wnt/β-catenin activation in TECs is related to advanced oxidation protein product-induced lipid accumulation, which is thought to contribute to renal fibrosis." (PMID 35517820, 2022). "Based on previous studies, LMWF can also alleviate renal fibrosis by regulating the CD36 factor." (PMID 34869779, 2021). "Thus, NF may initiate lipogenesis through the SREBP-1/2/AMPK pathway and lipid uptake by CD36 upregulation and aggravate renal fibrosis in vivo." (PMID 32575412, 2020). "Western blotting and immunohistochemical analysis showed that NF significantly induced TNF-α, CD36, SREBP-1/2, and acetyl-CoA carboxylase expression and renal fibrosis, and reduced fatty acid synthase and AMPK compared to other groups (p < 0.05)." (PMID 32575412, 2020). "In this study, we demonstrated that nifedipine may induce renal fibrosis and lipogenesis in a CKD animal model with a higher expression of CD36/SREBP-1/2 signals." (PMID 32575412, 2020). "Thus, CD36 plays an important roles in kidney diseases, but an increased expression of CD36-induced lipid accumulation is not a major contributor to renal fibrosis." (PMID 35517820, 2022).
anaemia (8 papers, 2009 to 2026). "The CD36 variant rs3211891_C is revealed for the first time as a potential modulator of anemia severity in SCA." (PMID 42207357, 2026). "Parasitaemia, anaemia and weight loss were similar between cd36−/− and wt controls and for both groups of mice the infections resolved with 100% survival." (PMID 28468674, 2017). "Even so, a number of marginal susceptibility genotype associations were also observed between specific gene mutations and anaemia (GBP7), CM (CD40LG), hyperparasitaemia (NOS2), hyperpyrexia (CD36, CD40LG, G6PD), SMA (EMR1) and UM (NOS2, EMR1)." (PMID 24934404, 2014). "By contrast, the lack of CD36 did not impact significantly on the course of a primary acute infection or on the accompanying anaemia and weight loss." (PMID 28468674, 2017). "Compared with anemia controls, the MDS and MA groups showed a significant increase in CD36 CV of CD105+NEC, and the CD36 RMFI in the MA group increased while that in the MDS group decreased." (PMID 37264109, 2023). "Compared with anemia controls (AC), the CD36 CV in MDS significantly increased (median 71.1 vs. 56.1, P = 0.002) and CD36 RMFI of CD105+ NEC was significantly decreased (median 360 vs. 512, P = 0.003)." (PMID 37264109, 2023). "Moreover, although CD36 RMFI of CD105+NEC may help distinguish between MA and MDS, further exploration is needed to differentiate MDS from other non-clonal anemia." (PMID 37264109, 2023).
ischemia (8 papers, 2009 to 2023). A hypoperfusion of the BLOOD through an organ or tissue caused by a PATHOLOGIC CONSTRICTION or obstruction of its BLOOD VESSELS, or an absence of BLOOD CIRCULATION. "Only the expression of CD36 was significantly decreased in aged hearts under acute ischemia compared to the young acute ischemia group." (PMID 37537789, 2023). "Their phagocytosis, mediated by TREM2, CD36, and other molecules, is critical in removing degenerating neuronal cells and debris after ischemia." (PMID 32174916, 2020). "Angiogenesis is the body response to ischemia and vascular injury and is inhibited by the interaction of CD36 with TSP-1." (PMID 19134193, 2009). "In this study, we found that the decreased expression of CD36 in the aged hearts during acute ischemia led to the downregulation of endogenous ligands (long‐chain fatty acid), which are the substrate for PPAR‐mediated transcriptional activation of fatty acid metabolism‐related genes." (PMID 37537789, 2023). "Because Cd36 can affect multiple physiological functions, we sought to directly examine whether myeloid-derived Vegfc regulates the myocardial response to ischemia." (PMID 35271504, 2022). "The ligands of CD36 produced during ischemia, such as thrombospondins, oxidized lipids, and apoptotic bodies, may upregulate its expression." (PMID 32174916, 2020). "In a healthy heart, a transporter of long-chain FAs, CD36, moves away from the plasma membrane and is replaced by GLUT4, representing a substantial shift from FA oxidation to glycolysis, which is associated with improved cardiac efficiency during ischemia." (PMID 29236774, 2017). "Compared to SIRT1f/f mice, icSIRT1−/− showed significant downregulation of PGC‐1α and carnitine palmitoyltransferase 1β (CPT1β) under acute ischemia, while PGC‐1α, CPT1β, and CD36 were reduced upon I/R stress." (PMID 37537789, 2023). "We also examined CD36 and CPT1 expression, and found that KD increased fatty acid uptake in limb tissue before ischemia but decreased its uptake after ischemia, indicating that ischemia interferes with the effect of KD on fatty acid uptake by limb tissue." (PMID 36038886, 2022). "In contrast to the result of increased CD36 and CPT1 gene expression found in non-ischemic tissue of mice fed with KD, they were decreased in limb tissue after ischemia indicating a decreased fatty oxidation by ischemia." (PMID 36038886, 2022).
lung fibrosis (8 papers, 2009 to 2025). "The scavenging receptor function of CD36 for apoptotic bodies has been implicated in the pathogenesis of pulmonary fibrosis." (PMID 38098035, 2023). "CD36 has also been implicated in lung fibrosis induced by silica." (PMID 38098035, 2023). "Next, GSEA on the changed proteins showed that secretome of lung fibrosis, mitochondria metabolism, cytokine signalling in immune system, cell death and ferroptosis‐related pathways were activated by CD36 knockout." (PMID 39083563, 2024). "In conclusion, our findings contribute to a growing literature that highlights CD36 as a key molecular driver of lung fibrosis." (PMID 38098035, 2023). "It has also been shown that macrophage CD36, involved in FFA transport, plays an important role in fibrogenesis since the loss of CD36 inhibits lung fibrosis." (PMID 37834305, 2023). "In this regard, we previously demonstrated that CD36 is required for pulmonary fibrosis following the instillation of apoptotic AEC2 cells into the lungs of healthy mice." (PMID 38098035, 2023). "CD36-null cells have increased expression of LPL, IL-6 and IL1-β which have been implicated in inflammasome assembly during bleomycin induced pulmonary fibrosis." (PMID 38098035, 2023). "With respect to the lung, our current results compliment the findings of two other reports that implicate CD36 in pulmonary fibrosis." (PMID 38098035, 2023). "Our central finding in the present study is the requirement of CD36 expression for the development of lung fibrosis following oxPL administration." (PMID 38098035, 2023). "The contribution of resident alveolar macrophages to the pathogenesis of lung fibrosis is less clear, but as mentioned, this population was markedly expanded in CD36-expressing WT mice on day 10 following oxPL instillation." (PMID 38098035, 2023). "One molecule that holds promise as a therapeutic target in pulmonary fibrosis is CD36 as several complimentary animal models of pulmonary fibrosis reveal that targeted deletion of the CD36 gene leads to protection against scarring." (PMID 38098035, 2023). "Specifically, Parks and colleagues demonstrated that CD36-null mice exhibited an attenuated capacity to clear apoptotic alveolar cells after bleomycin injury and that this decreased uptake of apoptotic bodies attenuated the severity of lung fibrosis." (PMID 38098035, 2023). "Although the mechanism by which it regulates lung fibrosis remains poorly defined, CD36 possesses multiple functions through which it could potentially mediate scarring." (PMID 38098035, 2023). "This hypothesis was supported by our data showing that CD36 was required for the development of lung fibrosis following apoptotic AEC2 administration." (PMID 38098035, 2023). "Based on the role of CD36 in oxPL binding and clearance and the recent findings that oxPL can drive lung fibrosis, we hypothesized that CD36 is critical in mediating fibrogenesis through its role in scavenging oxPL." (PMID 38098035, 2023). "Our data support the view that CD36 may contribute to the control of the activation of L-TGF-β1 and, therefore, silencing expression of CD36 could inhibit development of silica-induced lung fibrosis." (PMID 19439069, 2009). "CD36 may be involved in silica-induced lung fibrosis, because of its specific combination with TSP-1, which is a critical factor in the activation of L-TGF-β1." (PMID 19439069, 2009). "Collectively, these data support our hypothesis that CD36-mediated uptake and accumulation of oxPL in lung macrophages stimulates their production of TGFβ in the alveolar space and thereby potentiates the development of pulmonary fibrosis." (PMID 38098035, 2023). "We have shown that silencing expression of CD36 inhibits activation of L-TGF-β1, which results in reduced hydroxyproline, collagen synthesis, and further prevention of the development of lung fibrosis." (PMID 19439069, 2009).
lung fibrosis (continued). "CD36 takes part in the activation of latent TGF-β1 after binding to TSP-1 on the membrane of alveolar epithelial cells, which further contributes to the deposition of ECM and the progression of pulmonary fibrosis." (PMID 37593175, 2023). "We presume that silencing expression of CD36 could inhibit activation of L-TGF-β1 and result in prevention of the development of lung fibrosis." (PMID 19439069, 2009). "In the present study, considering the role of CD36 as a known scavenger receptor for oxPL and that apoptotic AEC2 cells are a rich source for oxPL, we sought to determine whether CD36 promotes the development of lung fibrosis in a novel murine model of intrapulmonary oxPL administration." (PMID 38098035, 2023).
non-small cell lung carcinoma (8 papers, 2019 to 2026). A group of at least three distinct histological types of lung cancer, including non-small cell squamous cell carcinoma, adenocarcinoma, and large cell carcinoma. "In a murine model of A427 non-small cell lung cancer (NSCLC) it was demonstrated that the toxin of Cyanobacteria decreases CD36 protein levels and increases the concentration of PARP1, an enzyme profoundly linked to tumor development." (PMID 35386685, 2022). "Inhibition of miR-21 was revealed to inhibit cell growth, migration, intracellular contents of lipids, and CD36 protein expression level in human non-small cell lung cancer cells." (PMID 31462892, 2019). "In addition, we also found inhibition of miR-21 suppressed cell growth, migration, intracellular contents of lipids, and CD36 protein expression level in human non-small cell lung cancer cells." (PMID 31462892, 2019). "In this study, lentivirus transfection, qRT-PCR, cell migration, immunofluorescence, and western blot were used to examine the relationship between miR-21 and CD36 regulated fatty acid metabolism and the regulation role of miR-21 in human non-small cell lung cancer." (PMID 31462892, 2019). "Moreover, down-regulation of CD36 suppressed miR-21 regulated cell growth, migration and intracellular contents of lipids in human non-small cell lung cancer cells." (PMID 31462892, 2019). "In addition, inhibition of miR-21 was revealed to inhibit cell growth, migration, intracellular contents of lipids, and CD36 protein expression level in human non-small cell lung cancer cells." (PMID 31462892, 2019). "However, the role of CD36 in HFD-accelerated non-small-cell lung cancer (NSCLC) is unclear." (PMID 38319449, 2024). "However, the relationship between miR-21 and CD36 regulated fatty acid metabolism in human non-small cell lung cancer remains unknown." (PMID 31462892, 2019). "CD36-positive CD8-positive T cells exhibit compromised immune functions, and a high level of infiltration of CD36-positive CD8-positive T cells predicts poor prognosis and inferior response to chemotherapy in patients with non-small cell lung cancer." (PMID 39744129, 2024).
periodontitis (8 papers, 2019 to 2025). An acute or chronic inflammatory process that affects the tissues that surround and support the teeth. "Elevated CD36 counts were independently associated with periodontitis and MetS, especially if occurring together, and CD36 expression in periodontal tissues was positively correlated with osteoclastogenesis." (PMID 37038173, 2023). "We have shown previously that CD36 expression in periodontal tissue is upregulated by MetS in mouse models of both periodontitis and MetS and upregulated in vitro by LPS and saturated fatty acids such as PA in macrophages." (PMID 39273569, 2024). "Palmitate-CD36 combination further increased the production of cytokines and chemokines, as well as elevated infiltration of critical inflammatory cells into the periodontitis niche, including monocytes and neutrophils." (PMID 36359775, 2022). "The percentage of CD197+ cells (M1 marker) was higher in response to periodontitis saliva than to healthy saliva, whereas the percentage of CD36+ cells (M2 marker) was lower." (PMID 36207325, 2022). "The expression of CD36 in periodontal tissues was detected to be elevated by the synergetic effects of periodontitis and a high-fat diet." (PMID 36359775, 2022). "Periodontitis saliva significantly reduced the percentages of CD14+, CD68+, and CD36+ cells versus healthy saliva, indicating a nudge of the monocytes and M0-type macrophages toward an inflammatory status but away from the M2 phenotype." (PMID 36207325, 2022).
prediabetes (8 papers, 2017 to 2025). "Particularly, Treg promoted T helper 17 differentiation and cytokine production in prediabetes, but not in DM, and showed overexpression of the fatty acid importer CD36, unveiling the critical role of host metabolome in controlling the immune response in prediabetes." (PMID 38667278, 2024). "The decreased IL-17A level and increased Cd36 expression in prediabetes mice indicated that the specific gut microbiota promoted the absorption of excess PA by disrupting the integrity of the intestinal mucous layer and regulating the expression of IL-17A and Cd36." (PMID 40878918, 2025).
adenoma (7 papers, 2018 to 2022). A neoplasm arising from the epithelium. "Since adenoma multiplicity is almost impossible to obtain, it is unknown if CD36 polymorphisms can be correlated with adenoma numbers." (PMID 33926505, 2021). "Here, we discover that CD36 expression is progressively decreased from adenomas to carcinomas." (PMID 31484922, 2019). "At present it remains to be revealed as to how CD36 could influence adenoma development, one possible mechanism is its role as an endogenous inhibitor of angiogenesis." (PMID 30065793, 2018).